INS (insulin)
Diseases named in the same sentence as INS in open-access papers (continued):
Sharing a sentence is not in itself a finding about the gene and the disease.
type 2 diabetes (continued). "This review attempts to describe the possible mechanisms related to insulin insensitivity, type 2 diabetes, and hypertension." (PMID 35455055, 2022). "Anti-diabetic effect: Rats with type 2 diabetes (T2D) showed an improvement after treatment with 500 mg/kg asparagus root extract due to a significant increase in insulin secretion." (PMID 37139102, 2022). "Pancreatic β-cells, which are required to supply a large amount of insulin rapidly under insulin-resistant conditions, such as type 2 diabetes, accumulate a large number of unfolded proteins in the ER and are thus vulnerable to ER stress." (PMID 35625542, 2022). "Eight weeks of regular green coffee consumption by people with type 2 diabetes not only improved fasting blood glucose but also increased the insulin sensitivity and glucagon-like peptide-1 (GLP-1) concentration compared to non-coffee drinkers." (PMID 36231426, 2022). "The levels of lipocalin-2 in tissues increases with metabolic disorders such as obesity and type 2 diabetes, indicating a link between lipocalin-2 and insulin sensitivity and glucose homeostasis." (PMID 36579566, 2022). "The result was consistent with the trends in the insulin resistance test, which indicated that the type II diabetes mouse model was successfully established." (PMID 36312255, 2022). "Another clinical trial study on type 2 diabetic patients has shown that oral consumption of ginger (1600 mg/d) for 12 weeks ameliorated insulin sensitivity and reduced C-reactive protein (CRP) and prostaglandin E2 (PGE2)." (PMID 35949312, 2022). "Type 2 diabetes mellitus (T2DM) is a chronic metabolic disorder characterized by impaired insulin secretion and/or action." (PMID 35625721, 2022). "Although the islet pathology in type 2 diabetes is typically focused on insulin and beta cells, increased glucagon secretion and alpha cell function can also contribute to hyperglycemia in type 2 diabetes." (PMID 36144204, 2022). "All five women with DKA and type 2 diabetes were treated with oral glucose‐lowering therapy and two were also treated with insulin prior to pregnancy." (PMID 34778994, 2022). "This pathological condition impairs insulin sensitivity and plays a relevant role in the pathogenesis of type 2 diabetes." (PMID 36014488, 2022). "Among the possible physiopathological mechanisms are the known effects of physical activity on improving sensitivity to insulin, decreasing the risks of type 2 diabetes, metabolic syndrome and inflammation." (PMID 35033022, 2022). "As mentioned in Section 4.3, alkaloids, namely lupanine, can potentiate the release of insulin by glucose, becoming a tool in the treatment of type II diabetes." (PMID 36500649, 2022). "In one small trial performed on a Japanese population with type 2 diabetes, it was found that intensive insulin treatment was related to the improvement in DSPN." (PMID 36387914, 2022). "Firstly, potassium, zinc, and calcium play an important role in improving glucose tolerance and indirectly contribute in the management of type 2 diabetes; in addition, calcium also plays an important role in insulin release from islet β-cells." (PMID 36277886, 2022). "Among the 59 women with type 2 diabetes, 16 patients forgot the specific duration of postpartum insulin use, and another 16 patients stopped using insulin immediately after discharge." (PMID 35585514, 2022). "Akbari et al21 showed that taking Co Q10 supplementation increased insulin sensitivity in type 2 diabetic patients and recommended taking this supplement in diabetic patients." (PMID 35919443, 2022). "Here the authors report that NaPB, an accelerator of BCAA catabolism, improves peripheral insulin sensitivity in patients with type 2 diabetes in a randomized placebo-controlled crossover clinical trial." (PMID 35717342, 2022). "A novel HIIT-protocol recruiting lower and upper body muscles efficiently improves insulin sensitivity, VO2max and body composition with intact responses in obesity and type 2 diabetes." (PMID 36387850, 2022).
type 2 diabetes (continued). "While the type 1 is usually associated with the destruction of pancreatic islet β-cell by the autoimmune process, the type 2 diabetes involves a combination of insulin resistance and defective compensatory insulin secretion." (PMID 35011523, 2022). "In type 1 diabetes, insulin must be used to maintain life, while in many patients with type 2 diabetes, it is necessary to increase the drug dose or choose combination drug therapy for better glycemic control." (PMID 35574009, 2022). "Type 2 diabetes mellitus (T2DM) is characterized by hyperglycemia and insulin insensitivity associated with a diminished incretin response, subclinical inflammatory processes, and impaired glucose tolerance." (PMID 35336098, 2022). "While insulin-suppressed LOX was unaffected by HIIT in men with type 2 diabetes and lean men, it increased in obese men." (PMID 36387850, 2022). "It is generally known that insulin can improve glycemic control in individuals with type 2 diabetes if they are well educated on how to adjust the dose." (PMID 35072900, 2022). "In the UK, for example, 2.4 people per 1000 of the adult population used insulin in 1991, and 0.7/1000 of these were considered to have type 2 diabetes." (PMID 35275238, 2022). "For example, UCP2 acts as a vital link between islet β-cell dysfunction and type 2 diabetes as a negative regulator of insulin secretion." (PMID 36266633, 2022). "Type 2 diabetes is chronic inflammation by increasing insulin resistance and disturbed glucose metabolism." (PMID 35562757, 2022). "Secondly, our results showed that the prevalence of EPI in type 2 diabetes patients was correlated with insulin usage, with more insulin requirement patients with a higher risk of EPI." (PMID 36213198, 2022). "In conclusion, melatonin treatment of male patients with type 2 diabetes for 3 months decreased insulin sensitivity by 12%." (PMID 35619221, 2022). "Future efforts are warranted to assess CNS insulin sensitivity in cognitive disorders other than type 2 diabetes and AD as well." (PMID 35884888, 2022). "This rationalizes the insulin sensitizing effects observed when rodent or human type 2 diabetics are fed spirulina." (PMID 36135209, 2022). "Adiponectin is a very potent insulin sensitizer, protecting from type-2 diabetes, and exhibits decreased serum levels in obesity and PCOS." (PMID 36289764, 2022). "In contrast to Type 2 diabetes, where peripheral cells become resistant to insulin over time, in T1D, pancreatic insulin-producing beta cells are destroyed by autoreactive T cells early on, with a particular pathogenic role of CD4+ and CD8+ cells." (PMID 35955407, 2022). "In the case of prediabetic and type 2 diabetic patients, IF can effectively reduce the glycated hemoglobin ratio, insulin levels, and insulin resistance." (PMID 35685418, 2022). "Type 2 diabetes was treated with either oral hypoglycemic drugs (n = 16, 76%), insulin (n = 4, 19%), or diet alone (n = 1, 7%)." (PMID 35739539, 2022). "Type 2 diabetes (T2D), the most common form in adults, is characterized by peripheral insulin resistance and relatively insufficient insulin secretion." (PMID 33751396, 2022). "Meanwhile, SFRP4 expression levels were significantly elevated in obese and type 2 diabetic patients, and increased β-cell dysfunction and suppressed insulin secretion." (PMID 36036283, 2022). "Adiponectin, mainly secreted from WAT but also from BAT, is a very potent insulin sensitizer and protects from type-2 diabetes and atherosclerosis." (PMID 36289764, 2022). "In a human, in vivo study we demonstrated that metformin reduces resistance of triiodothyronine and insulin in euthyroid, recently diagnosed type 2 diabetic patients." (PMID 36670938, 2022). "A clear and strong adipose methylome signature of obesity has emerged, with subsets of signals also relating to glucose and insulin homeostasis, lipid metabolism, and type 2 diabetes (T2D)." (PMID 35843982, 2022).
type 2 diabetes (continued). "Valeritas has introduced a V-Go (essentially hollow MNs), a disposable insulin injection device designed for adults with type II diabetes." (PMID 36151726, 2022). "The changes in fasting glucose and fasting insulin were in accordance with the results expected from the induction of type 2 diabetes by high-fat diet plus a low-dose of STZ." (PMID 36687680, 2022). "Combining a GLP-1 receptor agonist, to increase endogenous beta cell function, with exogenous insulin is a possible therapeutic option for the treatment of type 2 diabetes." (PMID 36244997, 2022). "Persons with LADA lose their ability to secrete insulin faster than those with type 2 diabetes but slower than type 1." (PMID 35923626, 2022). "Evidence from studies investigating the use of exogenous insulin to manage both type 1 and type 2 diabetes has demonstrated that intensive control of blood glucose through increased insulin use resulted in weight gain even when caloric intake was reduced." (PMID 35458121, 2022). "This is important as cold induced BAT thermogenesis improves insulin sensitivity and whole-body glucose homeostasis in healthy individuals and those with type 2 diabetes." (PMID 36017333, 2022). "A detailed past medical and surgical history revealed that the patient has diabetes mellitus type II, on insulin, and a surgical history of functional endoscopic sinus surgery, performed one year prior to presentation." (PMID 35186090, 2022). "Type 2 Diabetes Mellitus (T2DM) is a chronic disorder leading to hyperglycemia resulting from abnormal insulin function and secretion." (PMID 35733163, 2022). "Studies have also shown that hepatic ATP synthesis and content were reduced in high fat diet (HFD)-induced type 2 diabetic mice, insulin resistant-patients, and type 2 diabetic patients." (PMID 35800345, 2022). "Islet dysfunction is central in type 2 diabetes and full-blown type 2 diabetes develops first when the beta cells lose their ability to secrete adequate amounts of insulin in response to raised plasma glucose." (PMID 35482056, 2022). "Type 2 diabetes is a widespread metabolic disorder that results from various factors, including defective insulin secretion, the insulin resistance of insulin-sensitive tissues, ageing and environmental factors, such as stress and obesity." (PMID 35893954, 2022). "In type 2 diabetes, it has shown to improve insulin sensitivity and decrease plasma glucose in patients." (PMID 36550568, 2022). "In South Africa, initiating and managing insulin in primary care for people living with type 2 diabetes (PLWD) is a major challenge." (PMID 35924623, 2022). "Despite being the most effective treatment for advanced type 2 diabetes, the choice to start and maintain insulin therapy is based on a variety of criteria, including the patients' acceptance and willingness to adhere to it." (PMID 35854336, 2022). "MTORC1 activation in diet-induced obesity (DIO) is considered central to the pathophysiology, contributing to fat deposition in the liver, type-2 diabetes and insulin desensitization, lipogenesis, and other abnormalities." (PMID 35288456, 2022). "Despite the availability of multiple pharmacological options, including rapid-acting insulin analogs, postprandial hyperglycemia is highly prevalent in patients with both type 1 diabetes and type 2 diabetes." (PMID 36014822, 2022). "Throughout the development of type 2 diabetes, cells induce resistance against insulin, decreasing their ability to uptake glucose from the blood." (PMID 35956793, 2022). "In the subgroup analyses, the prevalence of EPI in type 2 diabetes was correlated to geographic location and insulin use." (PMID 36213198, 2022). "Those having type-II diabetes Mellitus would have some defects in the β-cells for the secretion of insulin." (PMID 35723344, 2022).
type 2 diabetes (continued). "Obesity leads to increased chronic low-grade inflammation, which impairs insulin signaling, contributing to the development of type 2 diabetes mellitus and cardiovascular diseases." (PMID 36015180, 2022). "Monitoring of retinal microvasculature using OCTA is of great importance for patients with type 2 diabetes who are receiving intensive insulin therapy." (PMID 35459162, 2022). "The results of in vivo animal experiments showed that the therapeutic effect of the MNP for type 2 diabetes was comparable to that of conventional subcutaneous insulin injection, with a relative bioavailability of 97%." (PMID 36151726, 2022). "GLP-1 is described as a potential target in the therapy of type 2 diabetes/obesity by means of repairing β-cell function and increasing insulin sensitivity in tissues." (PMID 35163196, 2022). "They suggest that beta cell dedifferentiation represents an alternative mechanism to explain the insufficient insulin production observed in type 2 diabetes." (PMID 35326375, 2022). "Type 1 and type 2 diabetes are pathological disorders defined by improper glucose, lipid, and protein metabolism as a result of defective insulin secretion or action." (PMID 35840638, 2022). "Type-1 diabetes is characterised by insufficient insulin release from the pancreatic cells, whereas type-2 diabetes is characterised by the development of the body’s insulin resistance." (PMID 35269321, 2022). "In this review, we provide an overview of the factors that regulate insulin removal from plasma and discuss the interrelationships among plasma insulin clearance, excess adiposity, insulin sensitivity, and type 2 diabetes (T2D)." (PMID 35054781, 2022). "Our present study showed similar results in FGMs and extends the applicability to patients with type 2 diabetes using premix insulin with more details on the changes of diet and exercise." (PMID 35222287, 2022). "In this study, we aim to investigate the correlation between sociodemographic characteristics, self-management, and glycated hemoglobin (HbA1c) values in patients with type 2 diabetes treated with insulin." (PMID 36292529, 2022). "In the mentioned study, the presence of type 2 diabetes was an exclusion factor; however, the insulin sensitivity was measured by the quantitative insulin-sensitivity check index (QUICKI)." (PMID 35215487, 2022). "Insulin obstruction is an element of type 2 diabetes, and parts of the cardiometabolic condition, including hypertension and dyslipidemia, which together add to an extensive hazard for cardiovascular disease." (PMID 35568318, 2022). "Injecting the incretin hormone Glucagon-like peptide-1 (GLP1) stimulates insulin production in type 2 diabetics; however, it is rapidly cleared by the kidneys in under 2 min." (PMID 36145580, 2022). "In the correlation group G9, an inverse relationship can be seen between having diagnosed type 2 diabetes and knowledge about insulin pump devices, CGMs, and artificial pancreas." (PMID 35712029, 2022). "Alzheimer’s disease (AD) and type 2 diabetes (T2D) are chronic diseases that share several pathological mechanisms, including insulin resistance and impaired insulin signalling." (PMID 36555450, 2022). "This study aimed to elucidate Sirt3′s molecular mechanism in regulating insulin sensitivity in adipocytes that can contribute to the effort of targeting Sirt3 for the treatment of obesity and type 2 diabetes." (PMID 35409099, 2022). "Despite research showing that many type 2 diabetic patients cannot maintain their blood sugar levels with just oral medication, some doctors are still hesitant to start insulin treatment." (PMID 36381916, 2022). "Insulin action; Insulin secretion; Middle East; Type 2 diabetes; Iraqi-born immigrants; Native Swedes." (PMID 36247141, 2022). "BS alters insulin secretion and sensitivity and contributes to the improvement or remission of type 2 diabetes post-operatively." (PMID 35328759, 2022).
type 2 diabetes (continued). "The core pathophysiologic defects in type 2 diabetes include beta‐cell failure and insulin resistance in muscle and liver." (PMID 35913467, 2022). "While type 1 diabetes is exclusively treated with the exogenous administration of insulin, people with type 2 diabetes and KPD can be treated with oral anti-diabetic tablets." (PMID 35462815, 2022). "Third, all participants were middle-aged, Caucasian, insulin-treated individuals with a relatively long duration of type 2 diabetes and the findings cannot be extrapolated to patients with other ethnicities or different medical background." (PMID 35379238, 2022). "Iron accumulation can affect the body’s sensitivity to insulin, Type 2 diabetes, liver disease and cardiovascular disease." (PMID 36335331, 2022). "A Japanese study showed that switching from insulin to IDegAsp coformulation significiantly improved glycemic control and reduced hypreducedng the at a 12 month follow-up of patients with type 2 diabetes." (PMID 36992737, 2022). "The CPI is widely used to asses endogenous insulin secretary reserves in both type 1 and type 2 diabetes." (PMID 35229479, 2022). "In human studies, women are generally more insulin sensitive than men, a difference which seems to diminish in the development of type 2 diabetes." (PMID 35050175, 2022). "Several epidemiological studies have reported that antioxidants supplementation reduced the blood insulin and lipids profile and both the DAI and the DAQS were inversely associated with four inflammation biomarkers among type 2 diabetes patients." (PMID 35600816, 2022). "Western-style diets, as defined by high intake of energy and fat, have been related to the rising prevalence of insulin-resistant states such as obesity and type 2 diabetes." (PMID 34704121, 2022). "These ROS kill beta cells and reduce insulin secretion, leading to hyperglycemia and Type II diabetes." (PMID 35204283, 2022). "We further demonstrated a putative causal role of genetically predicted type 2 diabetes and FIadjBMI in the development of PCOS, supporting a role of interventions on fasting insulin levels in the prevention of PCOS." (PMID 35771237, 2022). "On the other hand, multiple heart diseases, the insulin signaling pathway, and Type II diabetes mellitus were negatively correlated with LINC01480 by analyzing the negative co-expression genes." (PMID 35557532, 2022). "“I think besides the Triumphs Projects (a project using RLOs to guide type 2 diabetes patients making decision for insulin initiation), we are applying (the knowledge) to teach them this method (RLOs development)." (PMID 36126036, 2022). "This is a novel complementary approach to the insulin-mimetic actions of D-Pinitol in the context of diabetes type 2." (PMID 36235746, 2022). "Conceptually, these mice represent a model of severe type 2 diabetes, as they increase the production and secretion of less-active and immature insulin to keep glycemia under control." (PMID 35963866, 2022). "Deficiency of ms2t6A37 modification in tRNAlys (UUU) causes incorrectly translating the insulin mRNA AAG codon for lysine at the site of protease cleavage between the A-chain and the C-peptide and results in the development of type 2 diabetes." (PMID 36557225, 2022). "In particular, we focused on ER stress and its critical role in insulin synthesis and secretion, along with the β-cell dysfunction that occurs during the progression of type 2 diabetes and aging." (PMID 35563231, 2022). "Therefore, any excess observed in insulin users may be confounded because insulin use in type 2 diabetes patients is associated with duration and severity of the disease, thus explaining the excess compared with the population with type 2 diabetes on diet only." (PMID 35681699, 2022). "Despite multiple pharmacological options, including rapid-acting insulin analogs, postprandial hyperglycemia is still highly prevalent in patients with type 1 and type 2 diabetes." (PMID 36014822, 2022).